EPHA2 (EPH receptor A2)
Diseases named in the same sentence as EPHA2 in open-access papers (continued):
Sharing a sentence is not in itself a finding about the gene and the disease.
Age-related cataract (continued). "Recent studies have revealed that disruption of Eph-ephrin signaling, in particular the receptor EphA2 and the ligand ephrin-A5, in humans and mice lead to congenital and age-related cataracts." (PMID 34899394, 2021). "The putative role of EPHA2 in the etiopathogenesis of age-related cataract has attracted much attention regarding the molecular mechanisms involved in maintaining the clarity of lens by EPHA2." (PMID 26664742, 2015). "The gene for Eph-receptor tyrosinekinase-type A2 (EPHA2) has been shown to be involved in the pathogenesis of age-related cataract (ARC)." (PMID 21686326, 2011). "Our study identified EPHA2 as a gene for human age-related cataract and established Epha2 knockout mice as a model for progressive cortical cataract." (PMID 19649315, 2009). "The highest levels of association occurred with rs7543472 (allelic p<0.038 for cortical cataracts, and allelic p<0.021 for any age related cataracts) and rs11260867 (allelic p<0.020 for cortical cataracts), which lie just distal (3′) to EPHA2." (PMID 19005574, 2008). "For example, a mutant mouse model homozygous for a rare coding variant in EPHA2 (p.R722Q) associated with age-related cataract in humans did not develop cataract but did exhibit subtle defects in lens cell patterning and suture formation —consistent with a weak phenotypic effect." (PMID 38927721, 2024). "Ephrin-A5(-/-) and EphA2(-/-) mice, maintained mainly in the C57BL/6J strain background with wild-type Bfsp2 (or CP49) genes, develop congenital or age-related cataracts with incomplete genetic penetrance that is consistent with previous reports." (PMID 22140528, 2011). "In an initial screen, tagging SNPs covering the EPHA2 region were genotyped using 100 samples each from individuals with any nuclear, any cortical and no age-related cataracts." (PMID 19005574, 2008).
metastatic disease (16 papers, 2014 to 2025). "In colorectal tumors, EPHA2 overexpression was detected in approximately half of the samples and higher expression was associated with advanced stage tumors, metastatic disease and higher microvessels counts." (PMID 25193853, 2014). "ADAM12 is linked to the induction of EphA2-dependent cell migration in metastatic tumors." (PMID 33946495, 2021). "In the context of various cancers, EphA2 can also drive invasive metastatic disease and represents an important target for cancer therapeutics." (PMID 40411427, 2025). "ADAM12, ephrin-A1, and EphA2-contribute to growth or cell migration in primary and metastatic tumors." (PMID 33946495, 2021). "Nonetheless, several Eph receptors — notably EphA2 — have been proposed as therapeutic targets in oncology due to their aberrant expression in many cancers, which has been correlated with invasive and metastatic disease." (PMID 40411427, 2025). "In human tumors, EphA2 expression negatively correlates with PanIN lesions but increases in metastatic tumors;55 however, EphA2 is rarely genetically altered in human tumors, suggesting that protein expression and/or stability is deregulated during tumorigenesis." (PMID 33891893, 2021). "PTN, MK, PVRL4, EPHA2, TFPI-2, hK11, SYND1, ANGPT2 and hK14 were found elevated in the metastatic disease when compared to cancer-free, CPG1 and/or CPG5 groups." (PMID 33288843, 2021). "Finally, we identified the EPHs (EPHA2, EPHA4, EPHA8, and EPHB4) and EFNs (EFNA1, EFNA3, EFNA4, and EFNB2) that are significantly overexpressed in the aggressive epithelioid histological subtype and revealed that the majority of EPHs/EFNs are overexpressed in metastatic disease." (PMID 41516312, 2025).
cervical carcinoma (14 papers, 2008 to 2026). A carcinoma arising from either the exocervical squamous epithelium or the endocervical glandular epithelium. "Benign cervical cells even up-regulated EphA2 15-fold after HPV18 E2 expression, and EphA2 was also up-regulated in HPV-associated cervical carcinoma." (PMID 38136285, 2023). "Cancer cells very often express EphA2 ligands, including ephrinA1, which induces EphA2 Y588-phosphorylation in brain, breast, and cervical cancer." (PMID 39596256, 2024). "Noticeably, eukaryotic translation initiation factor 4E binding protein 1 (4EBP1) and EPH receptor A2 (EPHA2), which play important role in progression of cervical cancer, particularly in regulating migration and invasion, were hyperphosphorylated." (PMID 39567474, 2024). "This article explores the molecular mechanism of the cancer-promoting role of EphA2 in cervical cancer, and the results show that EphA2 promotes the proliferation, invasion, and metastasis of cervical cancer through the CXCL11/PD-L1 pathway." (PMID 36478746, 2022). "To further study the molecular mechanism of EphA2 in cervical cancer, we explored the downstream molecules of EphA2/CXCL11." (PMID 36478746, 2022). "Our experimental results show that EphA2 promotes the proliferation, invasion, and metastasis of cervical carcinoma through CXCL11." (PMID 36478746, 2022). "Our previous studies have shown that EphA2 has an indisputable cancer-promoting role in cervical cancer, but its related mechanism requires further research." (PMID 36478746, 2022). "Overall, we have reason to believe that EphA2 promotes the development of cervical cancer through the CXCL11/PD-L1 pathway." (PMID 36478746, 2022). "This study will be important for full understanding of the function of EphA2 in cancer malignancy and is also conducive to developing new treatment strategies for cervical cancer." (PMID 36478746, 2022). "It is believed that EphA2 affects the tumor microenvironment by promoting the autocrine chemokine CXCL11 in cervical cancer cells and further regulates the expression of PD-L1 on the cell surface." (PMID 36478746, 2022). "Our previous research has proved the cancer-promoting activity of EphA2 in cervical cancer, which was further confirmed in this study." (PMID 36478746, 2022). "Relevant experimental results showed that the expression level of EphA2 in cervical carcinoma was positively correlated with the malignant biological behavior ability of tumor cells and negatively correlated with an overall survival rate of patients." (PMID 36478746, 2022). "The threat of cervical carcinoma to a woman's life and health prompted us to seek more and better treatment methods, and EphA2 should receive more attention as a potential therapeutic target in cervical carcinoma." (PMID 36478746, 2022). "Our study demonstrated that EphA2 plays a tumor-promoting role in cervical carcinoma through the CXCL11/PD-L1 pathway, providing new guidance for the targeted therapy and combination therapy of cervical carcinoma." (PMID 36478746, 2022). "In this study, high-throughput sequencing was performed on EphA2 knockdown cervical cancer cells and the control group." (PMID 36478746, 2022). "Collectively, our study uncovered a possible cancer-promoting mechanism of EphA2 and proposed for the first time that EphA2 promotes the development of cervical cancer through the CXCL11/PD-L1 pathway." (PMID 36478746, 2022). "Although the cancer-promoting effect of EphA2 in cervical cancer has been confirmed, the related mechanism of its promoting effect in cervical carcinoma needs to be studied further." (PMID 36478746, 2022). "First, we detected the expression level of EphA2 in various cervical cancer cells, including Caski, HeLa, SiHa, and normal human cervical epithelial cells by qRT-PCR and Western blot analysis." (PMID 36478746, 2022). "Our previous results have confirmed that EphA2 is highly expressed in cervical carcinoma and tumorigenic both in vitro and in vivo." (PMID 36478746, 2022).
cervical carcinoma (continued). "At the beginning of this study, we performed an RNA sequencing analysis on EphA2 knockdown cervical cancer cells and controls." (PMID 36478746, 2022). "Our findings not only demonstrate the promoting effect of CXCL11 on the proliferation, invasion, and metastasis of cervical carcinoma but also the mediation of CXCL11 on the cancer-promoting effect of EphA2." (PMID 36478746, 2022). "The results of the transwell migration and invasion assay and the wound healing assay together demonstrated that the addition of CXCL11 rescued the inhibition of cervical carcinoma cell migration and invasion by the EphA2 knockout." (PMID 36478746, 2022). "To explore the molecular mechanism of EphA2's tumor-promoting effect in cervical cancer, we transfected SiHa cells with EphA2 knockdown small interfering RNA." (PMID 36478746, 2022). "This study is the first to propose that EphA2 plays a role in promoting cancer through the CXCL11/PD-L1 pathway in cervical cancer, which opens up new possibilities for targeted therapy and combined therapy of cervical carcinoma." (PMID 36478746, 2022). "In cervical cancer, EPHA2 activated AKT in a RhoG-dependent manner to promote the survival of HeLa cells." (PMID 33834064, 2021). "Collectively, these results suggest that CDK6 overexpression in EphA2 knock‐down cells restores oncogenic activity of the cervical cancer cells." (PMID 33586348, 2021). "To examine the role of endogenous soluble and membrane bound EFNA1 in the context of EPHA2 oncogenesis, we chose HeLa cells, an aggressive cervical cancer cell line that expresses both EPHA2 and EFNA1." (PMID 20979646, 2010). "Notably, p21 upregulation following EphA2 knockdown was observed specifically in cervical cancer cell lines." (PMID 41655696, 2026). "EPHA2 belongs to the ephrin-A receptor subfamily of the tyrosine kinase protein family and has been shown to have oncogenic functions in various cancer types, including cervical cancer." (PMID 40168262, 2025). "4EBP1 and EPHA2 play important roles in cervical cancer progression." (PMID 39567474, 2024). "Notably, the phosphorylation of 4EBP1 and EPHA2 in oeDDR1 cervical cancer cells was authenticated and verified by phosphoproteomics and western blot assay." (PMID 39567474, 2024). "To gain a more comprehensive understanding of the molecular mechanisms by which EphA2 exerts the tumor-promoting effect in cervical cancer, we performed an RNA sequencing analysis of EphA2 knockdown SiHa cells and SiHa cells that originally overexpressed EphA2." (PMID 36478746, 2022). "More studies are needed to verify this hypothesis and better understand the mechanism of EphA2 in cervical cancer." (PMID 36478746, 2022). "The experimental results indicated that EphA2 may play a role in promoting cancer through CXCL11 in cervical cancer." (PMID 36478746, 2022). "We speculate that targeting EphA2 combined with targeting PD-L1 can produce better efficacy than a single drug, that is, targeting EphA2 may enhance the sensitivity of cervical cancer to PD-L1-targeted therapy." (PMID 36478746, 2022). "The tumor biological functions of cervical cancer cells were decreased with EphA2 knockdown, whether in proliferation, invasion, or metastasis." (PMID 36478746, 2022). "Data from the CCK8 assay demonstrated that the knockdown of EphA2 led to the weakening of the proliferative capacity of cervical cancer cells, whereas the replenishment of CXCL11 leads to a significant recovery of the proliferative capacity of sh-EphA2-SiHa cells." (PMID 36478746, 2022). "Thus, FSCN1 negatively regulates four transcription factors (HLTF, HBP1, ZNF664, DDX17) and positively regulates ANGPTL4 (an angiogenic factor) and EPHA2 in both HeLa cells and cervical cancer tissues." (PMID 35178306, 2022). "That is, targeting EphA2 may improve the sensitivity of cervical cancer to PD-L1-targeted therapy." (PMID 36478746, 2022).
cervical carcinoma (continued). "Therefore, we speculate that there is a signal transduction pathway of EphA2/CXCL11/PD-L1 in cervical cancer." (PMID 36478746, 2022). "However, the role of EphA2 in cervical cancer (CC) is still needed to be further explored." (PMID 33586348, 2021). "To further demonstrate that CXCL11 mediates the cancer-promoting effect of EphA2 in cervical carcinoma, we analyzed the effect of CXCL11 on the proliferation ability of the sh-EphA2-SiHa cell line by the CCK8 assay." (PMID 36478746, 2022). "In addition, the reduced migration rate and invasive cell number, and attenuated phosphorylation of 4EBP1 and EPHA2 supported that DDR1 influenced the migration and invasion of cervical cancer via GRB2." (PMID 39567474, 2024). "In cervical cancer cells, CXCL11 was highly expressed when EphA2 was highly expressed." (PMID 36478746, 2022). "In addition, there was a significantly correlation between EphA2 protein and CDK6 protein expression in human cervical cancer tissues." (PMID 33586348, 2021). "Moreover, it has been reported in the literature that tumor cells affect the expression of PD-L1 in cells by autocrine CXCL11, so we have reason to believe that EphA2 upregulates PD-L1 through autocrine chemokine CXCL11, thereby promoting the occurrence and development of cervical carcinoma." (PMID 36478746, 2022). "However, the molecular mechanism of EphA2 in promoting cervical cancer has not been studied." (PMID 36478746, 2022).
triple-negative breast carcinoma (14 papers, 2019 to 2025). An invasive breast carcinoma which is negative for expression of estrogen receptor (ER), progesterone receptor (PR), and human epidermal growth factor receptor 2 (HER2). "EphA2 overexpression is observed in Her-2-enriched and triple-negative breast cancer (TNBC), the more aggressive subtypes of BCA, correlating with adverse prognostic outcomes." (PMID 38612592, 2024). "More specifically, evidence has shown that miR-200a can exert the anti-cancer effect on triple-negative breast cancer cells by direct repression of the EPHA2 oncogene." (PMID 36765782, 2023). "Targeting EPHA2 has decreased cell cycle progression and growth of basal-like/triple-negative breast cancers." (PMID 35646067, 2022). "Indeed, EphA2 has been evaluated as a drug target using multiple approaches, such as agonist antibodies in leukemia and small molecule inhibitors in triple-negative breast cancer." (PMID 34178975, 2021). "The current study aims to investigate the clinical significance of EPHA2, EPHA4, and EPHA7 expression in triple-negative breast cancer (TNBC) cases." (PMID 35204461, 2022). "The expression levels of IL-13Rα2 and EphA2 may exhibit variability among patients with HER-2 enriched and triple-negative breast cancer (TNBC)." (PMID 38612592, 2024). "The Eph family member EPHA2 has recently been proposed as a negative prognostic factor in triple-negative breast cancer (TNBC) patients; moreover, EPHA2 may act as a precision therapeutic target for this challenging condition." (PMID 36499024, 2022). "Taken together, our results demonstrate that brucine inhibits the migration, invasion, and vasculogenic mimicry in human triple-negative breast cancer cell line MDA-MB-231, which might be through the disruption of cytoskeleton and downregulation of EphA2, MMP-9, and MMP-2." (PMID 30723742, 2019).
medulloblastoma (13 papers, 2014 to 2026). A malignant, invasive embryonal neoplasm arising from the cerebellum. "Immunohistochemical studies have revealed that the presence of VM is associated with the expression of MMP-2, MMP-14, EphA2 and laminin 5γ2 in medulloblastoma." (PMID 25202424, 2014). "As one of the mechanisms of treatment resistance, loss of H3K27me3 results in increased expression of EPHA2, a tyrosine kinase that stimulates the AKT signaling pathway in medulloblastoma." (PMID 39636550, 2025). "EphA2 is highly expressed in medulloblastoma cell lines Res-300 and Uw-426, with moderate phosphorylation detected in Uw-402 following stimulation." (PMID 41200151, 2025). "The epithelial cell receptor protein kinase EPHA2 has been found to be particularly overexpressed on group 3 medulloblastomas and PFA ependymomas." (PMID 34771608, 2021). "EphB2 and its ligand ephrin-B1 have been shown to be highly expressed in medulloblastoma tissue samples, and EphA2, EphB2, and EphB4 are overexpressed in medulloblastoma cell lines." (PMID 33050158, 2020). "Interestingly, repeating i.c.v. administrations of EPHA2 CAR-T cells in medulloblastoma PDX models enhanced the overall survival in comparison to a single EPHA2 CAR-T cell treatment with no signs of severe systemic toxicities." (PMID 35885047, 2022). "Regarding EPH/ephrin members’ expression, upregulation of EPHB2 and ephrin-B1 has been reported in tumor samples compared to normal cerebellum, while EPHA2, EPHB2, and EPHB4 showed overexpression in medulloblastoma cell lines." (PMID 38612645, 2024). "EPHA2, HER2, and interleukin 13 receptors have all been identified as cell-surface targets expressed in medulloblastoma, with preclinical evidence to support a combination study." (PMID 37627881, 2023). "Targets include HER2, B7-H3, EPHA2, GD2, PRAME207, and Interleukin 13 receptor α2, most of which are known to be expressed on medulloblastoma tumor cells." (PMID 37627881, 2023). "Another study identified three cell surface targets, EPHA2, HER2, and IL13Rα2, that are expressed on medulloblastoma and ependymoma." (PMID 36983330, 2023). "EPHA2-specific CAR T cell therapy has been proven to be effective and safe in PDOX models of medulloblastoma and ependymomas, even though it is also detected at low levels on epithelial cells as well as on brain cells." (PMID 34771608, 2021). "The use of trivalent targets to EphA2, HER2, and IL-13Rα2 of CAR T cells exhibited benefits in preclinical models of recurrent medulloblastoma, GBM, and ependymomas." (PMID 33673696, 2021). "Thus, our study nominates EphA2-CAR T cells as a promising alternative to B7-H3-CAR T cells, which are actively being explored in clinical studies for medulloblastoma." (PMID 41756431, 2026). "Moreover, it confirmed that intrathecal delivery of EPHA2, HER2, and IL13Rα2 CAR-T cells is an effective treatment for primary, metastatic, and recurrent group 3 medulloblastoma and PFA ependymoma in a mouse model." (PMID 36983330, 2023). "Supporting this, microarray data from 29 medulloblastoma samples revealed subgroup-specific expression patterns: EphA2 is enriched in non-SHH tumors (WHO groups 3 and 4) but absent in SHH subtypes, suggesting a potential role in the pathobiology of more aggressive medulloblastoma variants." (PMID 41200151, 2025).
pancreatic adenocarcinoma (13 papers, 2009 to 2025). "More recent studies, underlined the role of EphA2 in driving therapy-resistant pancreatic adenocarcinomas, suggesting that EphA2 targeting agents should be developed and used in combination with current therapeutics." (PMID 32397624, 2020). "For example, in pancreatic adenocarcinoma-derived cells, sequence-specific siRNA targeting EphA2 suppresses EphA2 expression, retarding tumor growth in a nude mouse xenograft model." (PMID 32811512, 2020). "Small interfering RNA-mediated inhibition of EphA2 has been reported to retard tumour growth and inhibit metastasis in an in vivo study of pancreatic adenocarcinoma." (PMID 23738943, 2013). "Targeting of EphA2 with antisense oligonucleotides or monoclonal antibodies (mAbs) inducing proteosomal degradation of membrane-bound receptor reverses breast and pancreatic adenocarcinoma cell growth." (PMID 20130824, 2009). "Furthermore, a previous study showed that FAK was functionally important in EphA2 signaling and was a downstream effector in pancreatic adenocarcinoma cells." (PMID 26177500, 2015). "Staining of the EphA2 antibody in the human pancreatic adenocarcinoma tissue was evident in cancerous, but not in normal ducts and also in some fibroblast cells within stroma." (PMID 26959746, 2016).